CGAS (cyclic GMP-AMP synthase)
Description:
Nucleotidyltransferase that catalyzes the formation of cyclic GMP-AMP (2',3'-cGAMP) from ATP and GTP and plays a key role in innate immunity. Catalysis involves both the formation of a 2',5' phosphodiester linkage at the GpA step and the formation of a 3',5' phosphodiester linkage at the ApG step, producing c[G(2',5')pA(3',5')p]. Acts as a key DNA sensor: directly binds double-stranded DNA (dsDNA), inducing the formation of liquid-like droplets in which CGAS is activated, leading to synthesis of 2',3'-cGAMP, a second messenger that binds to and activates STING1, thereby triggering type-I interferon production. Preferentially recognizes and binds curved long dsDNAs of a minimal length of 40 bp. Acts as a key foreign DNA sensor, the presence of double-stranded DNA (dsDNA) in the cytoplasm being a danger signal that triggers the immune responses. Has antiviral activity by sensing the presence of dsDNA from DNA viruses in the cytoplasm. Also acts as an innate immune sensor of infection by retroviruses, such as HIV-2, by detecting the presence of reverse-transcribed DNA in the cytosol. In contrast, HIV-1 is poorly sensed by CGAS, due to its capsid that cloaks viral DNA from CGAS detection. Detection of retroviral reverse-transcribed DNA in the cytosol may be indirect and be mediated via interaction with PQBP1, which directly binds reverse-transcribed retroviral DNA. Also detects the presence of DNA from bacteria, such as M.tuberculosis. 2',3'-cGAMP can be transferred from producing cells to neighboring cells through gap junctions, leading to promote STING1 activation and convey immune response to connecting cells. 2',3'-cGAMP can also be transferred between cells by virtue of packaging within viral particles contributing to IFN-induction in newly infected cells in a cGAS-independent but STING1-dependent manner. Also senses the presence of neutrophil extracellular traps (NETs) that are translocated to the cytosol following phagocytosis, leading to synthesis of 2',3'-cGAMP. In addition to foreign DNA, can also be activated by endogenous nuclear or mitochondrial DNA. When self-DNA leaks into the cytosol during cellular stress (such as mitochondrial stress, SARS-CoV-2 infection causing severe COVID-19 disease, DNA damage, mitotic arrest or senescence), or is present in form of cytosolic micronuclei, CGAS is activated leading to a state of sterile inflammation. Acts as a regulator of cellular senescence by binding to cytosolic chromatin fragments that are present in senescent cells, leading to trigger type-I interferon production via STING1 and promote cellular senescence (By similarity). Also involved in the inflammatory response to genome instability and double-stranded DNA breaks: acts by localizing to micronuclei arising from genome instability. Micronuclei, which are frequently found in cancer cells, consist of chromatin surrounded by their own nuclear membrane: following breakdown of the micronuclear envelope, a process associated with chromothripsis, CGAS binds self-DNA exposed to the cytosol, leading to 2',3'-cGAMP synthesis and subsequent activation of STING1 and type-I interferon production. Activated in response to prolonged mitotic arrest, promoting mitotic cell death. In a healthy cell, CGAS is however kept inactive even in cellular events that directly expose it to self-DNA, such as mitosis, when cGAS associates with chromatin directly after nuclear envelope breakdown or remains in the form of postmitotic persistent nuclear cGAS pools bound to chromatin. Nuclear CGAS is inactivated by chromatin via direct interaction with nucleosomes, which block CGAS from DNA binding and thus prevent CGAS-induced autoimmunity. Also acts as a suppressor of DNA repair in response to DNA damage: inhibits homologous recombination repair by interacting with PARP1, the CGAS-PARP1 interaction leading to impede the formation of the PARP1-TIMELESS complex. In addition to DNA, also sense translation stress: in response to translation stress, translocates to the cytosol and associates with collided ribosomes, promoting its activation and triggering type-I interferon production. In contrast to other mammals, human CGAS displays species-specific mechanisms of DNA recognition and produces less 2',3'-cGAMP, allowing a more fine-tuned response to pathogens.
Synonyms: h-cGAS; C6orf150; MB21D1; D4
Tractability: Small molecule: a structure with a bound ligand is known; a high-quality ligand is known. Antibody: UniProt places it where antibodies can reach, with high confidence; its Gene Ontology location is reachable by antibodies, with high confidence. PROTAC: UniProt records ubiquitination sites on it; ubiquitination databases record sites on it; a small molecule that binds it is known.
Target class: Enzyme; Transferase
Chemical probes: RU.521
Gene: Protein-coding gene on chromosome 6 (73,413,515 to 73,461,726, reverse strand). Ensembl gene ENSG00000164430.
Subcellular location: Nucleus; Chromosome; Cell membrane; Cytoplasm, cytosol
Subcellular location (Human Protein Atlas): Nucleoplasm; Cytosol; Nuclear bodies
Pathways (Reactome):
Disease: Dengue virus activates/modulates innate and adaptive immune responses
Immune System: STING mediated induction of host immune responses
Gene Ontology:
Molecular function: 2',3'-cyclic GMP-AMP synthase activity; chromatin binding; DNA binding; double-stranded DNA binding; molecular condensate scaffold activity; nucleosome binding; phosphatidylinositol-4,5-bisphosphate binding; protein binding; protein homodimerization activity; poly-ADP-D-ribose modification-dependent protein binding; identical protein binding
Biological process: activation of innate immune response; antiviral innate immune response; cGAS/STING signaling pathway; cytoplasmic pattern recognition receptor signaling pathway; defense response to virus; DNA damage response; negative regulation of double-strand break repair via homologous recombination; paracrine signaling; pattern recognition receptor signaling pathway; positive regulation of defense response to virus by host; positive regulation of type I interferon production; cellular response to exogenous dsRNA; positive regulation of cellular senescence; negative regulation of DNA repair
Cellular component: chromosome; cytoplasm; cytoplasmic side of plasma membrane; cytosol; nuclear body; nucleoplasm; nucleus; plasma membrane; site of double-strand break
Genetic constraint (gnomAD): Loss-of-function variants: 26 observed, 23.57 expected, observed/expected ratio (o/e) 1.1, 90% interval 0.81 to 1.53. The upper end of that interval is the gene's LOEUF score, 1.53, which puts it in group 6 of 6, group 1 being the genes least tolerant of losing a copy. Missense variants: 542 observed, 581.64 expected, observed/expected ratio (o/e) 0.93, 90% interval 0.87 to 1. Synonymous variants: 249 observed, 236.99 expected, observed/expected ratio (o/e) 1.05, 90% interval 0.95 to 1.17.
Homologues: Orthologues: chimpanzee CGAS (97% identical), macaque CGAS (82% identical), pig CGAS (63% identical), mouse Cgas (55% identical), rat Cgas (54% identical), dog CGAS (52% identical), tropical clawed frog cgas (37% identical), zebrafish cgasa (30% identical), Drosophila melanogaster CG7194 (13% identical), Drosophila melanogaster cGlr2 (12% identical). Paralogues in human: ITPRIPL2 (17% identical), ITPRIP (15% identical), MAB21L3 (15% identical), MB21D2 (14% identical), MAB21L1 (12% identical), MAB21L2 (12% identical), ITPRIPL1 (12% identical), MAB21L4 (11% identical), TMEM102 (9% identical).
Diseases named in the same sentence as CGAS in open-access papers:
CGAS is named in the same sentence as 428 diseases in open-access papers, as found by Europe PMC text mining. Sharing a sentence is not in itself a finding about the gene and the disease. The quoted sentences say what the papers report.
viral infection (334 papers, 2016 to 2026). "Pathogenic factors such as viral infection can induce DNA damage and trigger the cGAS–STING signaling pathway, leading to enhanced production of IFN-β and nuclear translocation of NF-κB, thereby initiating inflammatory responses." (PMID 41008530, 2025). "Another study reported that HIV-2 Vpx (a naturally immunogenic virion-associated protein) suppressed cGAS-STING-mediated NF-κB signaling to promote viral infection." (PMID 38693578, 2024). "During the early phase of viral infection, tripartite motif-containing 38 (Trim38, an E3 ubiquitin ligase) stabilizes cGAS by preventing its Lys48 (K48)-linked ubiquitination and subsequent degradation." (PMID 36964253, 2023). "Although virus infections frequently cause intestinal manifestation, the cellular mechanism of the cGAS-STING pathway in intestinal mucosa during virus infection needs more research." (PMID 37781354, 2023). "Ring finger protein 185 (RNF185, an E3 ubiquitin ligase) interacts with cGAS during viral infections and specifically catalyzes the K27-linked polyubiquitination of cGAS at K137 and K384, enhancing the enzymatic activity of cGAS37." (PMID 36964253, 2023). "Collectively, our findings not only characterize a previously uncovered regulatory mechanism of cGAS activation but also provide potential targets for viral infection-caused diseases and autoimmune disorders." (PMID 36217001, 2022). "To further explore the mechanism underlying the regulation of cGAS in the context of viral infection, we performed co-immunoprecipitation (Co-IP) experiments in combination with mass spectrometry assays and identified PCBP2 as a cGAS-interacting protein." (PMID 35322803, 2022). "Collectively, these findings suggest that PCBP2 and cGAS form a complex in cells and the association of two proteins is likely modulated by viral infection." (PMID 35322803, 2022). "The association between PCBP2 and cGAS was detected under both normal physiological and viral infection conditions." (PMID 35322803, 2022). "The mis-localized cGAS causes strong interferon in response to genotoxic stress, but the cGAS response induced by viral infection is weakened." (PMID 35006471, 2021). "PPP6C is constitutively associated with cGAS in un-stimulated cells and disassociated upon virus infection." (PMID 33105828, 2020). "Upstream of STING, cGAS has been implicated in the recognition of multiple virus infections, including VACV." (PMID 31603920, 2019). "TRIM38 targets cGAS for SUMOylation in uninfected cells and during the early phase of viral infection, which prevents its K48-linked ubiquitination and degradation." (PMID 29546673, 2018). "Interestingly, we found that the nitrosylation-deficient pp65 mutants also immunoprecipitated with cGAS to similar levels as WT virus infection." (PMID 40243337, 2025). "It remains uncertain whether oxidative stress is the cause or the consequence of cGAS-STING signalling activation during viral infection." (PMID 38426093, 2024). "However, excessive cGAS activation leads to microglial pyroptosis after viral infection, trauma, stroke, and subarachnoid hemorrhage causing chronic neurodegenerative diseases." (PMID 36139387, 2022). "All CBASS systems encode a cGAS/DncV-like nucleotidyltransferase (CD-NTase; here termed cGAS) that synthesizes a cyclic di- or trinucleotide second messenger molecule, and a second-messenger activated effector protein that mediates cell death to abort the viral infection." (PMID 35536256, 2022). "Upon viral infection, the cGAS-STING axis is pivotal for initiating type I interferon (IFN) production against DNA viruses." (PMID 42112904, 2026). "In mammalian cells, the enzyme cyclic GMP-AMP synthase (cGAS) detects cytosolic double-stranded DNA (dsDNA), often indicative of viral infection or cellular damage, and catalyzes the formation of 2′3′-cGAMP from ATP and GTP." (PMID 41358758, 2026).
viral infection (continued). "RIG-I and STING are critical for mediating the RIG-I and cGAS-STING signaling pathways that guard against viral infection." (PMID 42113893, 2026). "It is also a key regulator of immune response to viral infections and a key cGAS-STING downstream chemokine involved in immune response." (PMID 40221409, 2025). "Intriguingly, a recent investigation revealed that nuclear cGAS can directly activate innate immune responses in dendritic cells (DCs) and macrophages during viral infection within the nuclear compartment." (PMID 40470467, 2025). "Recent investigations have elucidated that cGAS is also subject to regulation by SUMOylation, both in quiescent cellular states and in the context of viral infection." (PMID 40470467, 2025). "cGAS-STING signaling has a crucial role in the defence against viral infections, although in many chronic inflammatory diseases it aggravates the pathogenesis, such as in atherosclerosis and rheumatoid arthritis." (PMID 40542276, 2025). "The cGAS-STING system acts as a sensor for cytosol viral DNA upon viral infection and phage invasion." (PMID 40308709, 2025). "Truncation of cGAS NTD leads to cGAS mislocalization in cytoplasm and nucleus and hyper-response to genotoxic stress but a weaker response to viral infection." (PMID 39754705, 2025). "Cell stress during viral infection can lead to release of DNA into the cytoplasm, activating cGAS and inducing an interferon response to combat the infection." (PMID 39836220, 2025). "AGBL5 deglutamylation activity in particular, is required to activate cyclic GMP-AMP synthase and subsequent interferon response during viral infection." (PMID 40926193, 2025). "This pathway is crucial for mounting an effective immune response to viral infections; however, the activation of the cGAS/STING pathway must be tightly regulated to prevent uncontrolled inflammation and tissue damage." (PMID 41583428, 2025). "Intriguingly, AKT-mediated phosphorylation of cGAS at serine 291 (Ser291) has inhibited its enzymatic activity and attenuated the immune response to viral infection." (PMID 40470467, 2025). "The cGAS-STING pathway is also a key in viral infections, with TRIM30α induced by HSV-1 infection in dendritic cells, promoting STING degradation and acting as a negative feedback regulator of the innate immune response." (PMID 40028324, 2025). "For example, during viral infections, it can be activated via the cGAS/STING pathway in a SKY-dependent manner." (PMID 41367865, 2025). "Viral infection can trigger the cytoplasmic DNA sensor cGAS, recognizing cytosolic double-stranded DNA and producing the second messenger cGAMP to activate STING, possibly leading to the activation of NF-κB." (PMID 40503879, 2025). "This phenomenon is consistent with previous studies showing that the intrinsic apoptosis deficiency caused by knocking out Apaf-1 augments the IFN response in basal or viral infection conditions via the mtDNA-dependent cGAS-STING activation." (PMID 39833169, 2025). "The cGAS/STING-dependent innate immune pathway is central in the cellular response to cytosolic DNA derived from viral infections, genotoxic stress, or mitochondrial defects." (PMID 41411133, 2025). "In rotavirus, STAG2 deficiency induces IFN responses via the cGAS-STING pathway, ultimately restricting viral infection." (PMID 40981223, 2025). "cGAS is a key sensor of cytoplasmic DNA that triggers innate immune responses against cancer and viral infections." (PMID 41463247, 2025). "Cyclic GMP–AMP synthase (cGAS)–stimulator of interferon genes (STING) signaling pathway is an essential mechanism of response to DNA by regulating inflammation after viral infections and cellular stress." (PMID 41041557, 2025). "In summary, targeting the ion channel sensor Piezo1 in neutrophils alters NET DNA production and TLR9 and cGAS signalling activities, thereby contributing to the reciprocal differentiation of M1 and M2 macrophages while responding to viral infection." (PMID 39890818, 2025).
viral infection (continued). "Our study highlights two key biological roles of US1: inhibiting cGAS activation and facilitating viral replication, underscoring its critical function in subverting early innate immune defenses for successful viral infection." (PMID 41196926, 2025). "The dysregulation of ubiquitination in the cGAS-STING pathway is often associated with autoimmune diseases, viral infections, inflammation, and disturbances in intestinal homeostasis." (PMID 40028324, 2025). "In contrast, during viral infection, the cGAS-STING pathway quickly senses viral nucleotides released into the cytoplasm during the infection process, inducing T1IFN and its downstream effectors." (PMID 41181142, 2025). "Upon viral infection or lysosomal dysfunction, cGAS undergoes evident translocation to the cytoplasm, where it executes canonical functions." (PMID 40470467, 2025). "During the immune response to viral infection, the DNA receptor cGAS recognizes viral DNA as a danger signal and, activates STING, which initiates downstream signaling, promoting the expression of type I interferons." (PMID 39295867, 2024). "Studies have shown that poly(rC)-binding protein 1 (PCBP1) is recruited to the cGAS protein to increase its activity and enhance the affinity of cGAS for its ligand during viral infection." (PMID 38782895, 2024). "In uninfected cells or at the early stage of virus infection, TRIM38 targets cGAS to carry out sumoylation at K464 and K217 to prevent K48‐linked polyubiquitination and subsequent proteasomal degradation of cGAS." (PMID 38525112, 2024). "For example, SUMO E3 ligase Trim38 SUMOylated cGAS at K231 and K479 residues during the early phase of viral infection, preventing the polyubiquitination and protein degradation of cGAS." (PMID 38566133, 2024). "This work links defective AMFR-STING signaling to severe VZV disease and hyperinflammation and suggests a direct role for cGAS-STING in the control of viral infections in humans." (PMID 38277122, 2024). "During viral infection, the viral DNA can be recognized by the cGAS and activates the cGAS-STING pathway, triggering a series of immune and cellular responses to protect the body, including ER stress." (PMID 38426093, 2024). "These researches suggest that these host cellular responses play significant roles in cGAS-STING-mediated viral infection." (PMID 38426093, 2024). "The NF-κB pathway is widely recognized as the primary regulator of inflammation, while the cGAS-STING pathway has been shown to effectively induce NF-κB activity in response to viral infections." (PMID 39599510, 2024). "In conclusion, maintaining high levels of IFN by ensuring the cGAS-STING activity is critical for host resistance to viral infection." (PMID 38426093, 2024). "To address the role of each factor in the innate response against viral infection, we infected susceptible monocytic THP-1 cells WT or KO for STING, cGAS or IFI16 with NiV-eGFP or MeV-eGFP." (PMID 39283943, 2024). "The cyclic GMP-AMP synthase (cGAS)-stimulator of interferon genes (STING) is a crucial innate defence mechanism against viral infection in the innate immune system, as it principally induces the production of type I interferons." (PMID 38164186, 2024). "More and more multi-omics studies have confirmed the important role of cGAS-STING in the course of viral infections." (PMID 38426093, 2024). "Mitochondrial DNA released due to viral infection is detected by receptors (TLR-9, NOD-Like Receptor Thermal Protein Domain Associated Protein 3 (NLRP3), and cyclic GMP-AMP synthase (cGAS)) that typically identify viral or bacterial DNA." (PMID 39742024, 2024). "Treatment of swine cells with inhibitors of the cGAS/STING pathway or depletion of cGAS promoted viral infection, while overexpression of a mutant cGAS defective for cGAMP synthesis, unlike wild type cGAS, failed to reduce FMDV replication." (PMID 38509419, 2024).